ZNF266 (zinc finger protein 266)
Description:
May be involved in transcriptional regulation.
Synonyms: HZF1
Tractability: PROTAC: ubiquitination databases record sites on it.
Gene: Protein-coding gene on chromosome 19 (9,412,424 to 9,435,601, reverse strand). Ensembl gene ENSG00000174652.
Subcellular location: Nucleus
Subcellular location (Human Protein Atlas): Vesicles; Nucleoplasm; Rods & Rings
Pathways (Reactome):
Gene expression (Transcription): Generic Transcription Pathway
Gene Ontology:
Molecular function: protein binding; DNA-binding transcription factor activity, RNA polymerase II-specific; RNA polymerase II transcription regulatory region sequence-specific DNA binding; sequence-specific double-stranded DNA binding
Biological process: regulation of transcription by RNA polymerase II; regulation of DNA-templated transcription
Cellular component: nucleus
Genetic constraint (gnomAD): Loss-of-function variants: 12 observed, 13.23 expected, observed/expected ratio (o/e) 0.91, 90% interval 0.58 to 1.47. The upper end of that interval is the gene's LOEUF score, 1.47, which puts it in group 6 of 6, group 1 being the genes least tolerant of losing a copy. Missense variants: 680 observed, 670.35 expected, observed/expected ratio (o/e) 1.01, 90% interval 0.95 to 1.08. Synonymous variants: 240 observed, 231.68 expected, observed/expected ratio (o/e) 1.04, 90% interval 0.93 to 1.15.
Homologues: Orthologues: chimpanzee ZNF266 (99% identical), macaque ZNF266 (92% identical), rabbit ZNF266 (65% identical), mouse Zfp266 (50% identical), rat Zfp266 (50% identical), Drosophila melanogaster CG3281 (23% identical), Drosophila melanogaster CG2712 (20% identical), Drosophila melanogaster Phs (20% identical). Paralogues in human: ZNF778 (53% identical), ZNF846 (40% identical), ZFP90 (39% identical), ZNF560 (39% identical), ZNF555 (38% identical), ZFP37 (37% identical), ZNF599 (37% identical), ZNF404 (37% identical), ZNF264 (37% identical), ZNF805 (36% identical), ZNF10 (36% identical), ZNF20 (36% identical), and 50 more.
Diseases named in the same sentence as ZNF266 in open-access papers:
ZNF266 is named in the same sentence as 5 diseases in open-access papers, as found by Europe PMC text mining. Sharing a sentence is not in itself a finding about the gene and the disease. The quoted sentences say what the papers report.
leukemia (1 paper, 2021). A malignant (clonal) hematologic disorder, involving hematopoietic stem cells and characterized by the presence of primitive or atypical myeloid or lymphoid cells in the bone marrow and the blood. "Compared to healthy BMMCs, we observed the TF networks of ZNF266, RORA, GTF3C2, ZNF76, ZNF383, IRF5 and NFE2L2 being top upregulated in all leukemia patients." (PMID 33408321, 2021).
Lyme disease (1 paper, 2016). Lyme disease (named after the towns in the USA where the disease was first identified) is a bacterial infection caused by Borrelia burgdorferi. "When all of the time points were combined, a total of four different DEGs overall were identified in Lyme disease patients with persistent symptoms (non-PTLDS and/or PTLDS) compared to those with resolved disease, i.e., MIAT, CCDC163P, ZNF266, and GPR15." (PMID 26873097, 2016).
ZNF266 also shares sentences with these, for which no sentence is quoted: cervical cancer (1 paper); multiple sclerosis (1); tumor (1).